CCR2 (C-C motif chemokine receptor 2)
Diseases named in the same sentence as CCR2 in open-access papers (continued):
Sharing a sentence is not in itself a finding about the gene and the disease.
infection (341 papers, 2003 to 2026). The state of being infected such as from the introduction of a foreign agent such as serum, vaccine, antigenic substance or organism. "In the lung at 4 weeks post-infection, accumulation of Ly6Cpos macrophages and DCs declined by more than 80% in CCR2-deficient (Ccr2RFP/RFP) and DKO mice, while CX3CR1-deficient (Cx3cr1GFP/GFP) mice had preserved trafficking relative to Het mice." (PMID 40497732, 2025). "To measure the transport of Mtb to the MLN by infected lung cells, we quantitated the frequency of CCR7pos phagocytes at 4 weeks post-infection and observed that CCR2 deficiency was associated with more CCR7pos YFPpos Ly6Clo DCs in the lungs." (PMID 40497732, 2025). "We conclude that CCR2-deficient mice had impaired immune cell recruitment to the spinal cord relative to WT mice following EV-D68 infection." (PMID 40459936, 2025). "Monocytes, a complex population originating in the bone marrow, express various chemokine receptors, including CCR2, associated with inflammatory responses and infection defense." (PMID 40858671, 2025). "Contrastingly, CCR2-deficient mice exhibited a considerable increase in frequency due to infection, which was significantly higher than that observed in WT mice." (PMID 39051675, 2024). "IL-6 expression was upregulated by infection and tended to be lower in CCR2-deficient mice than in WT mice, although the difference was not statistically significant." (PMID 39051675, 2024). "In contrast, CCR2-deficient mice exhibited a more pronounced increase in these abnormalities following infection, the frequency of which was significantly higher than that observed in WT mice." (PMID 39051675, 2024). "AR complete CCR2 deficiency increases the risk of infection likely due to reduced numbers of tissue-resident monocyte-derived macrophages since CCR2 is critical to recruit monocytes into the lungs and other tissues." (PMID 38157855, 2024). "T. gondii DNA was detected in the placentas of both WT and CCR2-deficient mice after infection, with significantly higher levels in CCR2-deficient mice, indicating impaired T. gondii elimination in the placentas of CCR2-deficient mice." (PMID 39051675, 2024). "Strikingly, Ccr2−/− mice were highly susceptible and succumbed to infection beginning at 5 DPI, with all mice dying by 9 DPI, which is more severe than phenotype in Nos2−/− mice." (PMID 38352492, 2024). "CCR2+ inflammatory monocytes are required for host resistance to Toxoplasma and CCR2-deficient mice die during the acute phase of the infection." (PMID 38857298, 2024). "Strikingly, Ccr2–/– mice were highly susceptible and succumbed to infection beginning at 5 DPI, with all mice dying by 9 DPI, which is more severe than the phenotype in Nos2–/– mice." (PMID 39541153, 2024). "The delayed healing phenotype at 30 days post‐infection with a thick collagen capsule was evident in the CCR2‐deficient mice." (PMID 36424766, 2022). "Intrabullar injection of Haemophilus influenzae in mice that are depleted of macrophages by CCR2 deficiency and chlodronate liposomes results in prolonged neutrophilic infiltration in the middle ear mucosa and lumen and delayed clearance of infection." (PMID 36246635, 2022). "In CCR2-deficient mice, PbA infection induces a marginal increase in the lung edema of PbA-infected CCR2-deficient mice, and with PbNK65 infection no improvement in survival was reported, compared to wild-type (WT) mice." (PMID 35677654, 2022). "Mice deficient in the CCR2 chemokine receptor (its ligand), fail to recruit monocytes and succumb to infection." (PMID 34578186, 2021). "We find that mice deficient in CCR2 are highly compromised in their ability to survive intradermal infection with LVS, indicating the importance of this receptor during primary parenteral responses." (PMID 33760886, 2021). "When examining the lung draining mdLNs, we observed that CCR2 ablation in Clec9aΔCCR2 mice also compromised the infection-associated increase in mig-cDCs." (PMID 34739343, 2021).
infection (continued). "Further, anti-CCR2 significantly reduced lymphatic-associated monocyte populations following infection." (PMID 33434186, 2021). "Infection with an MCK-2 mutant virus results in reduced recruitment of patrolling (CX3CR1+) and inflammatory (CCR2+) monocytes to the site of infection, a reduced patrolling monocyte-associated viremia, and reduced viral titers in the salivary gland." (PMID 33508041, 2021). "On the other hand, complete CCR2 deficiency has different impacts on murine M. tuberculosis infection that vary with the route of infection and bacterial strain used." (PMID 33760886, 2021). "CCR2 deficiency impairs recruitment of Ly6Chi monocytes to infected sites and worsens infection with L. monocytogenes." (PMID 34367182, 2021). "Route-dependent differences in the susceptibility of CCR2-deficient mice have been noted previously during primary infection with other intracellular bacteria." (PMID 33760886, 2021). "Human genetic polymorphisms in gene alleles for CCR2 and its ligands have been associated with differential susceptibility to a number of infections of people, including malaria, HIV, Chagas disease, and Mycobacterium tuberculosis." (PMID 33760886, 2021). "Here, we directly evaluated systemic inflammatory monocytes during parenteral ID LVS infection of wild type mice or mice deficient in CCR2." (PMID 33760886, 2021). "Prior to infection, wildtype animals had an about 5-fold higher percentage of Ly6Chi cells, compared to CCR2-deficient mice." (PMID 34290699, 2021). "In a self-healing mouse model of intradermal infection with the human-pathogenic Karp strain of O. tsutsugamushi, we investigated the role of CCR2 on bacterial dissemination, development of symptoms, lung histology and monocyte subsets in blood and lungs." (PMID 34290699, 2021). "In animal models, deficiencies in CCR2 and some of its ligands alter susceptibility to several experimental infections, including those caused by intracellular pathogens." (PMID 33760886, 2021). "Susceptibility to secondary infection was thus inversely proportional to the extent of Mo expansion observed in CCR2- and CX3CR1-deficient mice, suggesting a protective role of Mo in these infectious conditions." (PMID 32425929, 2020). "CCR2-deficient mice are more resistant to infection due to better control of the circulating parasite." (PMID 31555297, 2019). "Ly-6Chi monocytes emigrate from bone marrow (BM) into the blood stream in a CCR2-dependent manner upon pathogenic infection, and then are recruited in inflamed tissues." (PMID 29760708, 2018). "CD11b+Ly-6Chi monocytes egress massively from the BM into the bloodstream in a CCR2-dependent manner upon pathogenic infection, and are then recruited into inflamed tissues via the CCR2-CCL2 axis." (PMID 29760708, 2018). "To block monocyte infiltration into the respiratory tract upon infection we engineered chimeric mice in which hematopoietic cells harbored mutations in the C-C chemokine receptor type 2 (CCR2)." (PMID 28256637, 2017). "A key difference between Ccr2—/—and Ifnar1—/—mice, however, is that CCR2 deficiency is favourable for infection outcome whereas Ifnar1—/—deficiency leads to enhanced mortality compared to WT animals." (PMID 26731100, 2016). "A protector effect of the CCR2-64I polymorphism with the susceptibilityof infection by HPV type 16 (OR = 0.35) was observed, suggesting a possible relation ofthis genetic variant with protection to HPV-16 infection." (PMID 26982176, 2016). "At day 9 after LCMV-Cl13 infection, iregDC expressed increased levels of the monocyte-associated proteins CCR2 (C-C chemokine receptor type 2) and FcγRI (CD64) in conjunction with the other monocyte-associated proteins FcεR1α, FcγRII/III, and Ly6C." (PMID 26808628, 2016).
infection (continued). "It has been shown that recruitment of Ly6Chigh monocytes into the lungs following exposure to C. neoformans is associated with control of the infection and is dependent on CCR2 and mice deficient in CCR2 are much more susceptible to C. neoformans infection." (PMID 26252005, 2015). "We therefore next investigated the consequences of CCR2 deficiency on BM hematopoiesis during acute infection with P. chabaudi." (PMID 23762028, 2013). "CCR2−/− mice infected with L. major are also more susceptible to infection due to an attenuated Th1 response." (PMID 23094119, 2012). "In this context, infected CCR2 KO mice exhibited lower levels of serum ALT than infected WT mice on day 28 post infection, i.e. when the lethal pathogenic features of the disease become apparent." (PMID 20714353, 2010). "CCR2 deficiency results in a dysregulated immune response characterized by excessive Th2 and Th17 polarization, ultimately compromising the host’s ability to control the infection." (PMID 39903705, 2025). "CCR2-deficient mice have a significant decrease in the migration of monocytes from the bone marrow to sites of infection, but as shown here and in other reports, Ly6Chi monocytes are still present in the MLN at approximately 10% of the level seen in wild-type animals." (PMID 39714174, 2025). "Loss of CCR2-dependent monocyte trafficking enhances clearance of Y. pseudotuberculosis, which is a surprising result as typically macrophages would be expected to be important to clear infections." (PMID 39541153, 2024). "Although we have associated miR-126 with tsc1 and the cxcl12a/ccl2/ccr2 axis by combinatorial gene depletion studies, miR-126 has been documented to be involved in additional pathways that may impact the outcome of infection." (PMID 38307625, 2024). "In addition, the accumulation of inflammatory monocytes in the placenta was reduced in CCR2-deficient mice during infection." (PMID 39051675, 2024). "Loss of CCR2-dependent monocyte trafficking enhances clearance of Yersinia pseudotuberculosis, which is a surprising result as typically macrophages would be expected to be important to clear infections." (PMID 38352492, 2024). "We hypothesized that deficiencies in either CCR2 or STAT1 proteins inhibit host defense against MmuPV1 infection, leading to increased viral replication and transcription in infected tongues." (PMID 38133335, 2023). "Furthermore, many of the CCR2‐deficient wounds were still hypervascularised at 30 days post‐infection." (PMID 36424766, 2022). "In contrast to the application of the CCR2 antibody MC-21, which depletes all CCR2-expressing cells including those in the bone marrow, we found an accumulation of bone marrow progenitors both in wild-type and CCR2-deficient mice at day 18 post infection." (PMID 33795674, 2021). "Consequently, CCR2 deficiency in mice drastically increases the susceptibility to infection with intracellular bacteria, viruses and protozoan parasites." (PMID 34290699, 2021). "Thus, the enhanced susceptibility of CCR2-depleted mice to infection with the fbp1Δ mutant is most likely due to the contributions of CCR2+ monocytes and mo-DCs." (PMID 29317510, 2018). "Finally, our model would predict that like Ccr2 deficiency, Sting deficiency should compromise the ability of wild-type bacteria to establish infection." (PMID 28844797, 2017). "Both Ccr2-deficiency and Sting-deficiency, which produced the expected decrease in infectivity of wild-type Mm upon hindbrain ventricle infection, failed to do so when the bacteria were delivered directly to monocytes through caudal vein infection." (PMID 28844797, 2017). "We observed that MC were significantly reduced in the lungs of CCR2-/- mice infected with L. pneumophila at days 3 and 5, and this was associated with a ~10-20-fold increase in bacterial burden 3 and 5 days after infection." (PMID 27300652, 2016).
infection (continued). "However, although at the point of secondary infection (5 dpi), we observe a trend to reduced alveolar macrophage numbers, their numbers are similar in resistant CCR2−/− and susceptible wild-type mice." (PMID 26265006, 2015). "Because recruitment of IMs in CCR2-deficient mice is defective throughout early, intermediate and late stages of infection, it has not been possible to specifically define the role of monocytes at different times during infection." (PMID 24220507, 2013). "On the other hand, Per1, also induced upon challenge, inhibits recruitment of Gr1-positive/Ccr2-expressing myeloid cells; interestinlgly, mainly neutrophils were affected, thus reducing host susceptibility, and mostly controling the immunopathology caused by infection." (PMID 41208953, 2025). "Therefore, CCR2 mice are severely susceptible to systemic ID LVS infection." (PMID 33760886, 2021). "Therefore, a higher expression level of CCR5 and CCR2 could favour a greater control of infection with T. cruzi and thus would be less susceptible to develop CCC." (PMID 30650073, 2019). "Infection of mice with YopM-producing Y. pestis caused a global effect in spleen that could protect the ΔyopM-1 strain in trans by preventing the stable accumulation of iDCs recruited through CCR2." (PMID 23248776, 2012). "Given the observed expansion of the MHC-II+CCR2+ HMs, we next investigatedmonocyte (MO) dynamics during infection." (PMID 41365681, 2026). "CCR2 is a chemokine receptor involved in recruitment of monocytes into tissues during infection and other inflammatory conditions." (PMID 41488698, 2026). "In this study, we observed a notable reduction in CD8+ T cells in the lungs of ccr2-/- mice following infection." (PMID 39903705, 2025). "To address this knowledge gap, we established a Chlamydia respiratory infection model in mice to investigate the impact of CCR2 on these infections." (PMID 39903705, 2025). "Four days after infection, the genes of chemokine receptors CCR2 and of TNF receptor 1 (TNFRSF1A) both involved in cell recruitment and orchestration of pro-inflammatory immune responses, were more highly expressed in the SLT-LS group compared to SLT-SS." (PMID 40079593, 2025). "Since significantly fewer Ccr2–/– mice developed paralysis following EV-D68 infection than did WT mice, we sought to define differences in the spinal cord immune cell profiles of Ccr2–/– and WT mice." (PMID 40459936, 2025). "The authors found that infection in Myh6-Cre hACE2 KI mice was rapidly cleared from the heart (by 7 days post-infection) and led to left ventricular systolic dysfunction, which was driven by CCR2-dependent infiltration of monocytes into the heart." (PMID 39861887, 2025). "To define the immune response to EV-D68 IL52 infection in WT and Ccr2–/– mice, we conducted Luminex-based assays for proinflammatory cytokines in spinal tissue of infected mice." (PMID 40459936, 2025). "In contrast, non-classical monocytes promote bacterial adaptability, exhibit a lower respiratory burst, and lack sufficient CCR2 expression, failing to migrate early to the infection site." (PMID 40092995, 2025). "The CCR2-mediated immune response is important for effective host resistance, particularly during the mid-phase of infection (day 7 p.i.), highlighting its critical role in managing both the inflammatory response and pathogen clearance." (PMID 39903705, 2025). "CCR2−/− and wild-type mice were infected with L. monocytogenes and 3 days post infection tissues were harvested for flow cytometry and CFU quantification." (PMID 39714174, 2025). "Host cells upregulate Ccl gene family members (e.g., Ccl2), which bind to receptors (e.g., CCR2) on immune cells, recruiting monocytes, macrophages, and memory T cells to infection sites." (PMID 40539063, 2025).
infection (continued). "A key function of CCR2 in inflammation involves recruiting monocytes and other components of the immune system to areas of tissue injury or infection, mainly via binding to its ligand CCL2 (monocyte chemotactic protein-1, MCP-1)." (PMID 40909274, 2025). "In L. neumophila infection, reduced monocyte migration from the bone marrow to infection sites in ccr2-/- mice results in fewer monocyte-derived DCs in the lungs, enhanced pathogen replication, and aggravated disease." (PMID 39903705, 2025). "Collectively, these findings demonstrate that live, replicating parasites were necessary to mobilize peripheral immune cells, including T cells and CCR2+ monocytes, into the brain during infection." (PMID 40492741, 2025). "Our findings indicate that CCR2 plays an important role in regulating the immune response during infection." (PMID 39903705, 2025). "C. muridarum infections induce CCR2 responses that are associated with the development of Th1 responses, the secretion of IFN-γ, and the clearance of local infection." (PMID 39903705, 2025). "Consistent with impaired T cell recruitment to sites of infection in Ccr2–/– and Rag1–/– mice, antibody-mediated depletion of CD4+ or CD8+ T cells from WT mice diminished paralysis." (PMID 40459936, 2025). "Next, we determined to confirm if inflammatory macrophages and moDCs regulate Th1 cells; we utilized Ccr2-/- mice that are defective in recruiting inflammatory macrophages and moDCs to the site of infection." (PMID 40294061, 2025). "The observation that MHCII was absent from lung DCs in CCR2ΔMHCII mice is consistent with prior observations that cDCs are recruited from the bone marrow to the lungs in a CCR2-dependent manner during infection." (PMID 40489538, 2025). "Together, these results agreed with a previous experiment performed several years earlier in our lab in which CCR2−/− and WT mice were infected with L. monocytogenes, and tissues were harvested 2 days post infection." (PMID 39714174, 2025). "Transcriptomic profiling revealed that H37Ra infection activated CCR2-dependent genes involved in immune response and apoptosis, including Trim30, Fas, and PD-1, which were reversed by CCR2 antagonists." (PMID 41562082, 2025). "Here, we use spatial transcriptomics to identify key genes that are upregulated in response to C. violaceum, and assess the importance of CCR2-dependent monocyte trafficking to the site of infection in the liver." (PMID 38352492, 2024). "During T. gondii infection, inflammatory monocytes expressing CCR2 are recruited to the infection site, resulting in the elimination of T. gondii in wild-type (WT) mice in a CCL2/CCR2 axis-dependent manner." (PMID 39051675, 2024). "Human complete CCR2 deficiency is a genetic etiology of PAP, polycystic lung disease, and recurrent infections caused by impaired CCL2-dependent monocyte migration to the lungs and infected tissues." (PMID 38157855, 2024). "We also evaluated the effects of CCR2 depletion on other cell types, by quantifying the main innate immune cell subsets in the BALF of WT and CCR2-depleted mice, 24 h post infection." (PMID 39418302, 2024). "At 24 h post infection, CCR2-depleted mice, despite possessing increased bacterial burdens, commonly accompanied with increased inflammation and cytokine release, displayed several cytokines with significantly lower levels compared to the control group." (PMID 39418302, 2024). "By 48 hours after inoculation, the infection was almost resolved in WT mice, whereas bacterial burdens were still significantly higher in CCR2-depleted mice (51.5-fold difference in BALF, p<0.001; 8.8-fold difference in lung, p<0.01)." (PMID 39418302, 2024). "We have observed that a reduction in miR-126 transcript alters normal macrophage phenotype and function through its involvement in the Cxcl12/Ccl2/Ccr2 axis and coupled with concurrent mTOR inhibition, increases cell death at the site of infection." (PMID 38307625, 2024).